DNAH5 (dynein axonemal heavy chain 5)
Description:
Force generating protein of respiratory cilia (By similarity). Produces force towards the minus ends of microtubules (By similarity). Key component of dynein, a family of motor proteins essential for movement along microtubules (By similarity). Dynein has ATPase activity; the force-producing power stroke is thought to occur on release of ADP (By similarity). Required for structural and functional integrity of the cilia of ependymal cells lining the brain ventricles (By similarity).
Synonyms: DNAHC5; HL1; PCD; CILD3; KTGNR
Tractability: Small molecule: a structure with a bound ligand is known. Antibody: its Gene Ontology location is reachable by antibodies, with medium confidence. PROTAC: ubiquitination databases record sites on it.
Gene: Protein-coding gene on chromosome 5 (13,690,328 to 14,011,818, reverse strand). Ensembl gene ENSG00000039139.
Subcellular location: Cytoplasm, cytoskeleton, cilium axoneme
Gene Ontology:
Molecular function: dynein intermediate chain binding; dynein light intermediate chain binding; minus-end-directed microtubule motor activity; ATP binding; microtubule motor activity
Biological process: cilium assembly; cilium movement; determination of left/right symmetry; flagellated sperm motility; outer dynein arm assembly; cilium movement involved in cell motility; microtubule-based movement
Cellular component: 9+2 motile cilium; axoneme; cytoplasm; motile cilium; outer dynein arm; 9+0 motile cilium; axonemal dynein complex; dynein complex
Genetic constraint (gnomAD): Loss-of-function variants: 349 observed, 499.3 expected, observed/expected ratio (o/e) 0.7, 90% interval 0.64 to 0.76. The upper end of that interval is the gene's LOEUF score, 0.76, which puts it in group 3 of 6, group 1 being the genes least tolerant of losing a copy. Missense variants: 5,311 observed, 5,751 expected, observed/expected ratio (o/e) 0.92, 90% interval 0.9 to 0.94. Synonymous variants: 1,983 observed, 2,065.5 expected, observed/expected ratio (o/e) 0.96, 90% interval 0.92 to 1.
Gene-disease validity (ClinGen):
ClinGen rates the evidence that DNAH5 causes each of these diseases.
primary ciliary dyskinesia 3 (autosomal recessive): Definitive.
Homologues: Orthologues: chimpanzee DNAH5 (99% identical), macaque DNAH5 (97% identical), guinea pig DNAH5 (91% identical), pig DNAH5 (91% identical), dog DNAH5 (90% identical), mouse Dnah5 (90% identical), rat Dnah5 (90% identical), rabbit DNAH5 (88% identical), tropical clawed frog dnah5 (81% identical), zebrafish dnah5 (77% identical), Drosophila melanogaster kl-3 (49% identical). Paralogues in human: DNAH8 (61% identical), DNAH10 (30% identical), DNAH2 (29% identical), DNAH9 (28% identical), DNAH17 (28% identical), DNAH11 (28% identical), DNAH1 (27% identical), DNAH3 (26% identical), DNAH7 (26% identical), DNAH12 (25% identical), DNAH6 (25% identical), DNAH14 (23% identical), and 3 more.
Diseases named in the same sentence as DNAH5 in open-access papers:
DNAH5 is named in the same sentence as 80 diseases in open-access papers, as found by Europe PMC text mining. Sharing a sentence is not in itself a finding about the gene and the disease. The quoted sentences say what the papers report.
primary ciliary dyskinesia (38 papers, 2014 to 2025). A rare, genetically heterogeneous, primarily respiratory disorder characterized by chronic upper and lower respiratory tract disease. "A previous study showed that mutations in the DNAH5 gene encoding dynein cause primary ciliary dyskinesia with outer dynein arm defects." (PMID 36836780, 2023). "Mutations in DNAH5 have been linked to primary ciliary dyskinesia (PCD), which is characterized by marked airway dysfunction." (PMID 35869121, 2022). "A literature review was also conducted to summarize DNAH5 mutations in pediatric patients with Kartagener syndrome across different ethnic groups." (PMID 34391405, 2021). "Two novel loss-of-function mutations in DNAH5 were identified and validated in a pediatric patient with Kartagener syndrome." (PMID 34391405, 2021). "DNAH5 mutations are a common cause of primary ciliary dyskinesia with outer dynein arm defects and DNAH5 has been regarded as a force generating of respiratory cilia." (PMID 32082391, 2020). "Rare mutations in DNAH5 can result in development of abnormal cilia and flagella in cells that lead to primary ciliary dyskinesia, which is a disorder characterized in part by chronic respiratory tract infections." (PMID 27515689, 2016). "In COPD, TLCCT was associated with a SNP in dynein, axonemal, heavy chain 5 (DNAH5), a gene in which genetic variants can cause primary ciliary dyskinesia." (PMID 25134640, 2014). "Dnah5 is associated with primary ciliary dyskinesia in humans." (PMID 39594631, 2024). "Abnormal expression of DNAH5 (which has previously been linked to genetic defects) has been implicated in chronic lower airway inflammatory diseases such as primary ciliary dyskinesia (PCD), Kartagener syndrome, bronchiectasis, and chronic obstructive pulmonary disease." (PMID 31798623, 2019). "A homozygous LOF variant was observed in DNAH5, which is a reported cause of primary ciliary dyskinesia (MIM 608644), an autosomal recessive condition that may involve complex cardiac malformations in a fraction of patients." (PMID 29089047, 2017). "Mutations in DNAH5 have previously been linked to primary ciliary dyskinesia (PCD), as well as non-syndromic asthenozoospermia and hypospadias." (PMID 41458559, 2025). "Dynein axonemal heavy chain 5 (DNAH5) is the most mutated gene in primary ciliary dyskinesia (PCD), leading to abnormal cilia ultrastructure and function." (PMID 36552777, 2022). "According to the literature, it has been shown that the mutations in dynein axonemal heavy chain 5 (DNAH5) have been accepted as one of the most common causes of Primary ciliary dyskinesia (PCD)." (PMID 36118901, 2022). "DNAH5 is associated with the onset of Primary Ciliary Dyskinesia (PCD), a respiratory disease characterized by recurrent infections of the respiratory tract and sperm immobility." (PMID 26305794, 2015). "Primary ciliary dyskinesia (PCD), a rare ciliopathy disorder, is caused by variants in multiple genes, with DNAH5 being one of the most frequently implicated." (PMID 40033371, 2025). "In the PubMed database, we used the keywords “primary ciliary dyskinesia,” “Kartagener syndrome,” “situs inversus,” “DNAH5,” and “China” for the search." (PMID 40224633, 2025). "The monogenic conditions identified included DNAH5-related primary ciliary dyskinesia, Burn-McKeown syndrome, Tatton-Brown-Rahman syndrome, SETD1B-related neurodevelopmental disorder, and SET-related disorder." (PMID 39695270, 2025). "Previous research has noted the association of several other dynein heavy chain-encoding genes, such as DNAH1, DNAH5, DNAH9, and DNAH11, with ciliary primary dyskinesia (PCD) and laterality defects." (PMID 36459505, 2022). "The diagnostic genetic variant rate identified using WES was 11.1% (8/72), in which primary ciliary dyskinesia (PCD)-associated gene mutations (CCDC40, CCDC114, DNAH5, DNAH11, and ARMC4) accounted for the vast majority (n = 5)." (PMID 35518361, 2022).
primary ciliary dyskinesia (continued). "We herein firstly reported a case of co-occurrence of Kartagener syndrome and MMS, who had a homozygotic nonsense mutation in DNAH5 gene, and heterozygotic missense mutation in the DNAH11 gene." (PMID 32847546, 2020). "As an example, DNAH11, DNAH5, DNAI1, and CCDC40 genes have been linked to primary ciliary dyskinesia." (PMID 33574797, 2020). "Mutation of DNAH5 is associated with primary ciliary dyskinesia (PCD, OMIM #608644)." (PMID 32859249, 2020). "Recent studies have demonstrated that mutations in other cilia dynein heavy-chain genes (such as DNAH5, DNAH9, and DNAH11) can cause primary ciliary dyskinesia (PCD)." (PMID 29843777, 2018). "Variants in the DNAH5 gene were significantly more frequent in Kartagener’s syndrome (KS) patients (32/55%) compared to those without KS (11/21.5%) (χ2 = 12.8; p = 0.0004; OR = 4.48)." (PMID 41373829, 2025). "When the patient was 14 years of age, multigene panel testing identified she was compound heterozygous for the pathogenic variants in DNAH5, associated with primary ciliary dyskinesia 3, with or without situs inversus." (PMID 39695270, 2025). "Dynein Axonemal Heavy Chain 5 (DNAH5) encodes dynein axonemal heavy chain, which is involved in ciliary assembly and cell motility and was initially found to be frequently mutated in patients with primary ciliary dyskinesia." (PMID 35501919, 2022). "In the present study, we provided the first comprehensive systematic review of genotype–phenotype associations in PCD patients harboring DNAH5 variants (primary ciliary dyskinesia-3, CILD3, OMIM#608,644)." (PMID 40033371, 2025). "Genetic mutations (DNAH5, DNAI1, and ZIC3) have been linked to the development of SIT, particularly in association with primary ciliary dyskinesia (PCD)." (PMID 40772152, 2025). "Recently, we have revealed that the aberrant localization of dynein axonemal heavy chain 5 (DNAH5), a ciliary ultrastructural marker primarily responsible for primary ciliary dyskinesia (PCD), correlates with the disease severity and eosinophilia in patients with NPs." (PMID 30459817, 2018). "Furthermore, the strongest interacted genes from our PPI data were primary ciliary dyskinesia-related genes DNAI1, DNAI2, and DNAH5, suggesting the role of cilia in CPAM." (PMID 37165378, 2023). "The combined mutation of DNAH5 and DNAH11 may lead to the overlapping dysfunction of motile and nonmotile cilia, which contribute to the co-occurrence of Kartagener syndrome and moyamoya syndrome." (PMID 32847546, 2020).
male infertility (14 papers, 2009 to 2025). The inability of the male to effect fertilization of an ovum after a specified period of unprotected intercourse. "The DNAH5 gene product is involved in the assembly of the outer axon dynein arm of flagella or cilia, and a mutation within this gene contributes to a risk of male infertility." (PMID 35887003, 2022). "Currently, 13 members of the DNAH gene family have been reported, including DNAH1 to DNAH3, DNAH5 to DNAH12, DNAH14, and DNAH17, among which 11 genes (DNAH1, DNAH2, DNAH5 to DNAH12, and DNAH17) are associated with male infertility." (PMID 38312775, 2024). "In humans, there are 13 dynein axonemal heavy chain (DNAH) proteins (DNAH1–3, DNAH5–12, DNAH14, and DNAH17) and mutations in many of these genes have been associated with male infertility." (PMID 36140773, 2022). "Mutations in dynein genes (DNA11, DNAH5, and DNAH11) have been linked to a common cause of male infertility in humans, asthenozoospermia, which is inherited in a dominant sex-specific manner." (PMID 19503617, 2009). "However, mutations in DNAH5, DNAH11, and DNAI1 also lead to male infertility due to isolated non-syndromic asthenozoospermia." (PMID 36726469, 2022). "Recent studies and expression analysis have shown that motile cilia dynein heavy chains DNAH5 and DNAH11 are not present in sperm, which suggests that mutations in these genes do not cause male infertility." (PMID 34573892, 2021).
Hydrocephalus (9 papers, 2007 to 2025). Hydrocephalus is an active distension of the ventricular system of the brain resulting from inadequate passage of CSF from its point of production within the cerebral ventricles to its point of absorption into the systemic circulation. "Our research indicates that Dnah5 deficiency-induced downregulation of Dync1h1 is involved in cortical development abnormalities and hydrocephalus progression." (PMID 39594631, 2024). "Hydrocephalus was associated with DNAH5 mutation in a mouse model." (PMID 33999288, 2021). "All Dnah5−/− mice developed hydrocephalus, confirmed by electron microscopy, indicating the absence of axonemal outer dynein arms." (PMID 39594631, 2024). "Hydrocephalus in the Dnah5−/− mouse model was found to arise from the stagnation of CSF due to impaired motile ciliary function and cortical malformations due to cytoplasmic dynein deficiency." (PMID 39594631, 2024). "Hydrocephalus and situs inversus occurred in all and 26% of homozygous individuals among the Dnah5−/− mice." (PMID 39594631, 2024). "Mutant mice with deficiencies in motile cilia axonemal proteins, such as hydin, dynein axonemal heavy chain 5 (Dnah5), and coiled-coil domain-containing 151 (Ccdc151), exhibit hydrocephalus." (PMID 36859317, 2023). "Mice deficient in genes coding for dynein assembly factors or dynein arm complex proteins (e.g., Dnah5) develop severe postnatal macrocephaly due to hydrocephalus, which is fatal within approximately a month." (PMID 37104040, 2023). "The occurrence of PCD and hydrocephalus has been reported in the past and has been shown to be associated with mutations in various genes (DNAI1, DNAH5, DNAH11, DNAI2, KTU, and RSPH9/4A)." (PMID 33999288, 2021). "Dnah5-null and Ccdc151-knockout animals both show very similar phenotypic traits, such as hydrocephalus, early postnatal lethality and defect in left-right body axis specification." (PMID 31383820, 2019). "Dnah5-knockout animals developed a very early severe and fast-progressing hydrocephalus with early postnatal lethality." (PMID 31383820, 2019). "Moreover, hydrocephalus is frequently observed across murine motile-cilia gene knockouts (e.g., DNAH5, DNAAF1) but remains uncommon in human PCD except in rare ciliogenesis disorders (e.g., CCNO, FOXJ1), underscoring a rodent–human discrepancy." (PMID 41477643, 2025). "Hydrocephalus in Dnah5−/− mice may result from cortical maldevelopment due to cytoplasmic dynein deficiency, further exacerbating ventricular enlargement due to CSF stagnation caused by impaired motile ciliary function." (PMID 39594631, 2024). "In particular, elucidating the mechanisms of hydrocephalus onset due to Dnah5−/− offers valuable insights that may inform not only traditional therapies but also new approaches and therapeutic targets." (PMID 39594631, 2024). "For example, in the animal model of PCD caused by lack of DNAH5 protein, mice lacking DNAH5 display hydrocephalus, which is not present in humans with DNAH5 mutations." (PMID 34044844, 2021). "Therefore, we used a knockout mouse model of Dnah5, a representative causative gene for PCD, and focused on (i) changes in the cerebral cortex immediately after birth and (ii) changes in the ventricular wall before the onset of hydrocephalus to identify the mechanisms underlying hydrocephalus." (PMID 39594631, 2024).
Infertility (9 papers, 2018 to 2025). "Among women with known genetic results, those with infertility had DNAH5, DNAAF3, ZMYND10, CCDC40, RSPH9 and HYDIN mutations." (PMID 40142748, 2025). "Main genetic mutations involved in pathology are the DNAI1 and DNAH5 genes result in compromised ciliary motility, leading to a predisposition for recurrent sinopulmonary infections, infertility, and anomalies in left–right body orientation." (PMID 40337424, 2025). "In KS, mutations in the DNAI1 and DNAH5 genes result in impaired ciliary motility, leading to a predisposition for recurrent sinopulmonary infections, infertility, and anomalies in left–right body orientation." (PMID 40337424, 2025). "In contrast, DNAH5 has not previously been associated with infertility in women, but 7 out of 15 women in our study with a mutation in DNAH5 were infertile." (PMID 38962571, 2024). "Compared to adults, pediatric DNAH5-mutated PCD patients displayed a higher incidence of NRD but a lower occurrence of bronchiectasis and infertility." (PMID 40033371, 2025). "We found that the clinical manifestations of DNAH5-mutated PCD patients were highly variable, with randomization of LR asymmetry, respiratory symptoms and infertility, which is consistent with previous studies." (PMID 40033371, 2025). "Since, in the male reproductive system, DNAH5 is expressed exclusively in the efferent ductules, if infertility occurs, it is caused by defects in motile cilia but not in sperm flagella." (PMID 39682722, 2024). "Other dynein family members, DNAH5 and DNAH1, are associated with infertility." (PMID 34199109, 2021).
situs inversus (9 papers, 2022 to 2025). A congenital condition in which there is complete right-to-left reversal of the position of the major thoracic and abdominal organs (that is, they are arranged in a mirror image of the normal positioning). "A total of 36% of situs inversus cases in our study were associated with the following genes: DNAH5, DNAI1, DNAI2, DNAAF5, and LRRC56." (PMID 37892347, 2023). "In our coorte, the DNAH5 mutation was found in two individuals with situs inversus." (PMID 36980814, 2023). "Three DNAH5 mutant individuals demonstrated situs inversus, indicative of impaired nodal cilia function." (PMID 40558543, 2025). "The male sibling did not have bronchiectasis or situs inversus, but the female sibling did, indicating that DNAH5 deficiency had different effects on the two siblings." (PMID 40142748, 2025). "Second, we found a heterozygous pathogenic stop-gain variant in the DNAH5 gene, a dynein involved in primary ciliary dyskinesia type 3, with or without situs inversus (MIM:608644) and reported as autosomal recessive." (PMID 36675175, 2023). "Indeed, a recent case report of mutations in the dynein heavy chain genes, DNAH5 and DNAH11 has raised the possibility of a link between situs inversus and developmental dyslexia." (PMID 35873488, 2022).
asthenozoospermia (7 papers, 2009 to 2025). "We found 1 of 143 asthenozoospermia patients was detected as carrying DNAH5 compound heterozygous variants (c.3502G>A and c.2578–11_2578-7del)." (PMID 32664073, 2020). "We discussed the possible association between mutations in DNAH5 and asthenospermia for the first time in Chinese people." (PMID 32664073, 2020). "In our study, 1 of 143 asthenozoospermia patients was detected as carrying DNAH5 compound heterozygous variants (c.3502G > A and c.2578-11_2578-7del)." (PMID 32664073, 2020). "In this study, the asthenozoospermia patient who carried DNAH5 compound heterozygous variants (c.3502G > A and c.2578-11_2578-7del) could use assisted reproductive technology to obtain offspring through genetic counseling." (PMID 32664073, 2020). "However, we report the possible association between variants in DNAH5 and asthenospermia for the first time in Chinese people." (PMID 32664073, 2020). "In addition to the normal variants detected in patients and controls, we found 2 mutations specific for asthenospermia (in the DNAH5 gene) with a frequency of 7.5 ‰ (1/134)." (PMID 32664073, 2020). "In the present study, we screened 143 patients with asthenozoospermia for variants in DNAH5 gene." (PMID 32664073, 2020). "In this report, we design to provide clues to prove relationship between dynein heavy chain gene 5 (DNAH5) gene alterations and asthenozoospermia." (PMID 32664073, 2020).